NCAM1 (neural cell adhesion molecule 1)
Description:
This protein is a cell adhesion molecule involved in neuron-neuron adhesion, neurite fasciculation, outgrowth of neurites, etc. (Microbial infection) Acts as a receptor for rabies virus. (Microbial infection) Acts as a receptor for Zika virus.
Synonyms: CD56; NCAM; MSK39
Tractability: Small molecule: it has a high-quality binding pocket. Antibody: a drug acting on it is in phase 2 or 3 trials; UniProt places it where antibodies can reach, with high confidence; its Gene Ontology location is reachable by antibodies, with high confidence; UniProt predicts a signal peptide or a membrane-spanning region; the Human Protein Atlas places it where antibodies can reach. PROTAC: ubiquitination databases record sites on it; its protein half-life has been measured. Other modalities: a drug acting on it is in phase 2 or 3 trials.
Target class: Adhesion
Gene: Protein-coding gene on chromosome 11 (112,961,275 to 113,278,436, forward strand). Ensembl gene ENSG00000149294.
Subcellular location: Cell membrane (Isoform 1); Cell membrane (Isoform 2); Cell membrane (Isoform 3); Cell membrane (Isoform 4); Secreted (Isoform 5); Secreted (Isoform 6)
Subcellular location (Human Protein Atlas): Plasma membrane; Cytosol; Predicted to be secreted
Pathways (Reactome):
Developmental Biology: NCAM signaling for neurite out-growth; NCAM1 interactions; Signal transduction by L1
Extracellular matrix organization: ECM proteoglycans
Immune System: Interferon gamma signaling
Signal Transduction: RAF/MAP kinase cascade
Gene Ontology:
Molecular function: protein binding
Biological process: cell adhesion; commissural neuron axon guidance; epithelial to mesenchymal transition; regulation of semaphorin-plexin signaling pathway
Cellular component: cell surface; cytosol; external side of plasma membrane; extracellular matrix; membrane; plasma membrane; Golgi membrane; neuron projection; extracellular region
Genetic constraint (gnomAD): Loss-of-function variants: 14 observed, 100.64 expected, observed/expected ratio (o/e) 0.14, 90% interval 0.091 to 0.22. The upper end of that interval is the gene's LOEUF score, 0.22, which puts it in group 1 of 6, group 1 being the genes least tolerant of losing a copy. Missense variants: 752 observed, 1,111.6 expected, observed/expected ratio (o/e) 0.68, 90% interval 0.64 to 0.72. Synonymous variants: 405 observed, 448.91 expected, observed/expected ratio (o/e) 0.9, 90% interval 0.83 to 0.98.
Homologues: Orthologues: chimpanzee NCAM1 (99% identical), macaque NCAM1 (98% identical), dog NCAM1 (95% identical), guinea pig NCAM1 (95% identical), rabbit NCAM1 (95% identical), rat Ncam1 (94% identical), mouse Ncam1 (94% identical), pig NCAM1 (94% identical), tropical clawed frog ncam1 (74% identical), zebrafish ncam1b (60% identical), zebrafish ncam1a (57% identical). Paralogues in human: NCAM2 (29% identical), ROBO2 (22% identical), ROBO1 (21% identical), CNTN4 (21% identical), CNTN3 (21% identical), CNTN2 (20% identical), CNTN5 (20% identical), CNTN1 (20% identical), CNTN6 (20% identical), NEO1 (20% identical), ROBO3 (20% identical), HMCN2 (19% identical), and 24 more.
Diseases named in the same sentence as NCAM1 in open-access papers:
NCAM1 is named in the same sentence as 655 diseases in open-access papers, as found by Europe PMC text mining. Sharing a sentence is not in itself a finding about the gene and the disease. The quoted sentences say what the papers report.
neuroblastoma (98 papers, 1998 to 2025). Neuroblastoma (NB) is the most common solid, extracranial childhood tumor. "Our results suggest that L1 interferes with NCAM1 transcription by causing intron retention in neuroblastoma and teratocarcinoma cell lines as well as in different human tissues." (PMID 22022525, 2011). "Protein abundance of KCNH1 was comparable to targets under development in neuroblastoma including NCAM1, L1CAM and CD276, and higher than other known immunotherapeutic targets such as ALK and GPC2." (PMID 38895237, 2024). "Formaldehyde crosslinking of mouse neuroblastoma Neuro-2a cells, followed by affinity purification, led in 2001 to a first report on a next-neighbor relationship of PrPC and NCAM1." (PMID 27879349, 2016). "Moreover, from the translational perspective, huN901-DM1 is currently being evaluated as monotherapy in children with various NCAM1-expressing solid tumors including: Wilms tumor, rhabdomyosarcoma, neuroblastoma, malignant peripheral nerve sheath tumor and synovial sarcoma." (PMID 31477684, 2019). "In our previous work using a mouse model with neuroblastomas, we demonstrated reversible, high-affinity binding of I-131-labeled ERIC1 to NCAM1, with Kd values of 9 × 10−8 M." (PMID 39408967, 2024). "NCAM1 (CD56) was subsequently detected in various tumors of neuroectodermal origin, such as neuroblastoma; rhabdomyosarcoma; various brain tumors; and, notably, small cell lung carcinoma." (PMID 39408967, 2024). "We used NCAM1 (CD56), an established cell surface molecule expressed in neuroblastoma as a marker for the plasma membrane and found NCAM1 and CAMKV proteins co-localize on the plasma membrane of NGP cells." (PMID 32211329, 2020). "Additionally, NCAM-1 (CD56) is a glycoprotein overexpressed on surface of neuroendocrine cancers, including SCLC and neuroblastoma." (PMID 40007813, 2025). "For example, NCAM1 (also known as CD56) is a main carrier for the neural crest stem cell marker and its reduced expression is correlated with unfavorable prognosis in neuroblastoma with distant metastases, regardless of the MYCN amplification status." (PMID 28984200, 2017).
COVID-19 (92 papers, 2020 to 2026). A disease caused by infection with severe acute respiratory syndrome coronavirus 2. "Moreover, compared to the control group, AD and COVID-19 were associated with a significantly reduced percentage of cluster 3 characterized by neural cell adhesion molecule 1 (NCAM1), neural cell adhesion molecule 2 (NCAM2), and glial fibrillary acidic protein (GFAP)." (PMID 36211330, 2022). "The results indicate that the production of anti-NCAM1 autoantibodies following COVID-19 is unlikely." (PMID 40687082, 2025). "We analyzed serum samples from 173 patients that were collected 3 months after COVID-19 using a cell-based assay that had been previously validated for the detection of anti-NCAM1 autoantibodies." (PMID 40687082, 2025). "NCAM-1 levels remained elevated during and after the onset of COVID-19, suggesting evidence of ongoing peripheral nerve injury." (PMID 34944606, 2021). "Thus, this study investigated the presence of anti-NCAM1 autoantibodies in individuals affected by COVID-19, including those with long COVID." (PMID 40687082, 2025). "Nonetheless, even if additional cases were classified as long COVID, our conclusion remains that anti-NCAM1 autoantibodies are not commonly associated with COVID-19." (PMID 40687082, 2025). "Neurodegeneration during the course of COVID-19 may be associated with an immune response against external structures of SARS-CoV-2, which shows molecular mimicry to NCAM-1 found in the central nervous system." (PMID 38673514, 2024). "In this study, (NCAM1+CD160+)NK cells increased significantly in all of the SARS-CoV-2 infected individuals compared to the HC and were positively correlated with the disease severity, suggesting that this NK cell subset may play both protective and pathogenic roles in the pathogenesis of COVID-19." (PMID 35281000, 2022). "We found that several neurodegeneration markers (YKL40, NCAM-1, CCL23) were elevated in survivors of COVID-19 in a sustained fashion." (PMID 34944606, 2021). "Here, we found that convalescents of COVID-19 have significantly lower S100 and significantly higher NCAM-1 serum concentrations than individuals who have never had contact with SARS-CoV-2." (PMID 38673514, 2024). "We found that COVID-19 convalescents had a lower serum concentration of NCAM-1 than those subjects who have never been infected with SARS-CoV-2." (PMID 38673514, 2024). "However, no anti-NCAM1 autoantibodies were detected in any of the serum samples collected 3 months after the COVID-19 diagnosis." (PMID 40687082, 2025). "However, the presence of anti-NCAM1 autoantibodies in individuals following COVID-19 has not yet been investigated." (PMID 40687082, 2025). "As we showed that COVID-19 convalescents are characterized by lower NCAM-1 serum concentrations than never-infected individuals, we suppose that the observed effect may be associated not with neurodegeneration but with possible immune system activity." (PMID 38673514, 2024). "The sustained elevation of YKL40, NCAM-1, and CCL23 may represent an ongoing pathological process in the survivors of COVID-19 as the levels did not decline below those recorded at admission." (PMID 34944606, 2021).
neuroendocrine tumors (84 papers, 2008 to 2026). "We further annotated tumor cells using four markers closely associated with neuroendocrine tumors: ASCL1, NCAM1, INSM1, and GRP." (PMID 40213972, 2025). "Traditional markers for neuroendocrine tumors comprise synaptophysin, chromogranin A, and CD56 (NCAM1)." (PMID 34884272, 2021). "SCLC is a high-grade neuroendocrine tumor that commonly expresses neuroendocrine markers, such as chromogranin A, synaptophysin, and neural cell adhesion molecule 1 (NCAM1)." (PMID 34948300, 2021). "Furthermore, genes encoding canonical markers of neuroendocrine tumors—including CHGA (chromogranin A), SYP (synaptophysin), NCAM1 (CD56), and ENO2 (neuron-specific enolase)—were all differentially higher in s3 tumors." (PMID 36731467, 2023). "However, IHC can discriminate between neuroendocrine and non-neuroendocrine tumors to determine cytological and tissue diagnoses, for which the neuroendocrine markers synaptophysin, chromogranin A, and NCAM1, also known as CD56, are very useful." (PMID 33202998, 2020). "Since SCLC is classified with neuroendocrine tumors, immunohistochemistry is very important in the diagnosis of SCLC, especially some neuroendocrine markers, such as Synaptophysin (Syn), Chromogranin A (CgA) and CD56 (an alias for neural cell adhesion molecule 1)." (PMID 34168983, 2021). "Finally, SCLCs and large cell neuroendocrine carcinoma (LCNEC) are neuroendocrine tumors (NETs) that usually have neuroendocrine differentiation properties and are defined by the specific expression of chromogranin A (CHGA), synaptophysin (SYP), and neural cell adhesion molecule 1 (NCAM1)." (PMID 35962452, 2022).
lymphoma (75 papers, 2010 to 2026). A malignant (clonal) proliferation of B- lymphocytes or T- lymphocytes which involves the lymph nodes, bone marrow and/or extranodal sites. "Together, EATL appears driven by STAT3-mediated inflammation and immune evasion, while MEITL is a cytotoxic lymphoma with high expression of innate-like T/NK-cell genes (e.g., STAT4, NCAM1) and an “immune-cold” profile with low inflammation." (PMID 41057685, 2026).
melanoma (67 papers, 2002 to 2025). A malignant, usually aggressive tumor composed of atypical, neoplastic melanocytes. "CD56 (NCAM1) as well as CD274 (PD-L1) were only detected in metastatic melanoma cells and primarily on a protein-only level consistent with the overall detection pattern for these markers in liquid and solid cohorts." (PMID 37563418, 2023). "We also looked up various genes classically expressed by Schwann cell precursors or Schwann cells and found that Gap43, Fabp7, Mpz, Dhh, Ngfr, Ncam1, and Mbp were all significantly upregulated in the sparse pigment tumors than in the intradermal melanomas, as was Plp1." (PMID 39804140, 2025). "Among these genes, we confirmed up-regulation of integrin α3 (ITGα3), CD24 and NCAM1 (CD56) at the protein level, which have been previously connected to increased aggressiveness of melanoma cells." (PMID 28199980, 2017). "On the other hand, the top downregulated genes formed 4 subgroups and were related to melanogenesis (Wnt5a, Mitf, Pomc, Mc1r, Kit), melanoma (Fgf9, Fgf12, Fgf2), MAPK signaling pathway (Ncam1, Prkcb, Map3k4, Pla2g4a, Mapk14, Mapk11), and aging (Tgfbr1, Il6, Nox4)." (PMID 36555664, 2022).
myeloma (67 papers, 2006 to 2026). "RP11-629G13.1 is a long noncoding RNA associated with downregulation of NCAM1 gene expression in multiple myeloma patients." (PMID 37985822, 2023).
breast carcinoma (66 papers, 2006 to 2026). "We also investigated the effect of mutant vimentin downregulation on breast cancer stem cell markers CD56/NCAM1 and CD201/PROCR in C328S-VIM-expressing cells upon shRNA treatment." (PMID 40690373, 2025). "Data analysis using FlowJo v10 confirmed significant upregulation of breast cancer stem cell markers CD56/NCAM1 and CD201/PROCR in C328S-VIM-expressing MCF-7 cells." (PMID 40690373, 2025). "The upregulated differentially expressed breast cancer stem cell markers included CD56/NCAM1, POU5F1, PROCR/CD201, ITGA6, and the downregulated were ESR1, PGR, HER2/ERBB2, ABCG2, CD44, CD24, EPCAM, and CDH1." (PMID 40690373, 2025). "NMUR1 and NCAM1 are novel key disease-causing genes for luminal A breast cancer, and STIL is a novel key disease-causing gene for basal-like breast cancer." (PMID 33066779, 2020). "Of the key genes unique to the luminal A breast cancer subtype, the expression levels of only NMUR1 and NCAM1 were associated with patient survival time (P < 0.05)." (PMID 33066779, 2020). "In summary, we identified NMUR1 and NCAM1 as novel key genes associated with the development, progression, and prognosis of luminal A breast cancer, and STIL as a new target with the prognosis of basal-like breast cancer." (PMID 33066779, 2020). "We identified NMUR1 and NCAM1 as novel key genes associated with the development, progression, and prognosis of luminal A breast cancer, and STIL as a novel key gene associated with the prognosis of basal-like breast cancer." (PMID 33066779, 2020). "Thus, we predict that inhibition of NMUR1 and NCAM1 could represent a novel strategy to improve the treatment of luminal A breast cancer." (PMID 33066779, 2020). "We found that luminal A breast cancer patients with high expression of NMUR1 and NCAM1 had statistically worse overall survival than patients with below-median levels of expression." (PMID 33066779, 2020). "The roles of NMUR1 and NCAM1 in breast cancer have not been reported." (PMID 33066779, 2020).
glioma (54 papers, 2006 to 2025). A benign or malignant brain and spinal cord tumor that arises from glial cells (astrocytes, oligodendrocytes, ependymal cells). "In line with this, we detected in patient data that increased expression levels of NCAM1 in low-grade glioma are associated with improved survival rates." (PMID 37880732, 2023). "A previous study reported that NCAM1 expression was associated with the invasive growth of glioma." (PMID 25860484, 2015). "NCAM-1 signaling plays an important role in neuronal cell migration, growth, and axon guidance, which has been shown to be expressed by tumor cells in gliomas and medulloblastomas, which we also observed in our SHH, Group 3, and Group 4 datasets." (PMID 39659836, 2024). "NCAM-1, when overexpressed in glioma cells, plays an important role in neuronal and glial cell adhesion, and therefore can be used as a target for treatments aimed at glioma cells." (PMID 40574222, 2025). "Some regulators of MRM were associated with the expression of NCAM1, NCAM2, and L1CAM, which indicated that MRM may facilitate glioma development via astrocytic modulation." (PMID 38824202, 2024). "NCAM1 expression correlates positively with the survival rate in low-grade glioma patients." (PMID 37880732, 2023). "Neural Cell Adhesion Molecule 1 (NCAM1), a member of the immunoglobulin superfamily of adhesion molecules, is associated with neurogenesis, synapse growth, cell proliferation, and migration in various cancers such as gliomas, ovarian carcinomas, and small-cell lung carcinomas." (PMID 40908816, 2025). "Although loss of NCAM1 expression in gastric cancer has not been reported before, our current data on the inverse association with gastric cancer invasion is consistent with previous studies of gliomas." (PMID 25860484, 2015). "The effects of serotonergic neurons on glioma cells are mediated by both known (e.g. NLGN3) and previously underappreciated growth factors such as ICAM-1 and NCAM-1, and through activation of the serotonin receptor HTR2A." (PMID 41427306, 2025). "Because only glioma-related proteins were used for targeted quantification, only the GGH and NCAM1 proteins showed differential abundance between moyamoya disease patients and healthy controls." (PMID 32922940, 2020). "CLIC4 expression levels were positively correlated with specific markers of macrophages (CD80, CD86, MRC1), neutrophils (FCGR3A, FCGR3B), eosinophils (SIGLEC8, IL3RA), T cells (CD3D, CD4), CD8+ T cells (CD8A, CD8D), NK cells (NCAM1), and B cells (CD19) in glioma." (PMID 39595145, 2024).